BGN (biglycan)
Diseases named in the same sentence as BGN in open-access papers (continued):
Sharing a sentence is not in itself a finding about the gene and the disease.
cancer (continued). "The data suggest that higher expression of BGN plays an oncogenic role in cancer migration and invasion." (PMID 31739592, 2019). "For instance, biglycan has been reported to either induce cancer cell invasion or to inhibit metastasis." (PMID 30947697, 2019). "BGN expression in MKN-45 cancer cells was upregulated and then knocked down to examine the reproducibility of the finding." (PMID 24681892, 2014). "Biglycan (BGN) is an important member of small leucine-rich proteoglycans family, and has been implicated in oncogenesis and development of various human cancer types." (PMID 24681892, 2014). "Biglycan was detected in the sera from nine of cancer patients but was hardly detected in those of four healthy volunteers, and the representative results are shown." (PMID 22374465, 2012). "Biglycan was detected in the sera of cancer patients but was hardly detected in those of healthy volunteers." (PMID 22374465, 2012). "Ductal cells from all three major NSG demonstrated Biglycan expression while in both the benign and malignant tumors the protein was almost exclusively expressed in the extracellular matrix (ECM) compartment, with both luminal and myoepithelial cells being negative." (PMID 39155517, 2025). "In HER-2-positive cancers, the oncogenic signaling pathway suppresses biglycan expression." (PMID 41304707, 2025). "A higher BGN expression level was found in advanced-stage cancer." (PMID 38740818, 2024). "There is also evidence from other cancer types that RAC1b, TAp73 and BGN all promote chemoresistance and that they may even operate through the same downstream signaling, i.e., NF-κB." (PMID 38255305, 2024). "This study suggests that biglycan derived from CAFs may be an unfavorable indicator for immunotherapy response and overall survival in cancer patients, and that it is a potential therapeutic target to overcome immunotherapy resistance." (PMID 37174001, 2023). "BGN was predominantly expressed in fibroblasts/myofibroblasts (CAFs) in various cancers." (PMID 36772945, 2023). "Considering that BGN is generally upregulated in tumors, we suspected that it may participate in cancer development and further influence patients’ clinical outcomes." (PMID 36772945, 2023). "Our in vivo data suggests that biglycan may be inhibiting the initial outgrowth of cancer cells in the brain." (PMID 37456245, 2023). "Indeed, Kaplan–Meier analysis indicated that lower BGN expression level predicted favourable OS in most cancers." (PMID 36772945, 2023). "BGN was highly expressed and mainly localized to the cytoplasm of cancer cells." (PMID 35789548, 2023). "Additionally, BGN appears to be highly expressed in cancer stem cells, such as colon and MCF-7-derived breast CSCs." (PMID 36358747, 2022). "Biglycan may perform its activity through intercellular contact, which is overexpressed in cancer stem cells and may activate NF-κB signaling." (PMID 36510567, 2022). "Furthermore, biglycan has been suggested to regulate the function of antigen-presenting cells, including macrophages and dendritic cells, with implications in cancer." (PMID 35267503, 2022). "In addition to the role of BGN expressed within cancer cells, it is also available in a secreted soluble form which is involved in various biological functions." (PMID 35053617, 2022). "Thus, BGN expression was evaluated at protein level in bulk cancer cells and BCSCs using immunoblotting." (PMID 35053617, 2022). "Recently, the role of biglycan has been investigated in cancer cells." (PMID 33966638, 2021). "This study revealed that BGN could be utilized as prospective treatment targets and biomarkers for multiple human cancers, especially for GC." (PMID 34868341, 2021). "Moreover, we utilized TCGA to explore BGN expression in pan-cancers and found that BGN was highly expressed in most cancer types." (PMID 34868341, 2021).
cancer (continued). "While still relatively undefined, these data suggest that BGN may promote cancer progression and that its expression is favoured by elevated mechanical cues." (PMID 34449016, 2021). "We previously showed that biglycan is highly expressed in TECs and facilitates cancer metastasis." (PMID 33966638, 2021). "The vast majority of research on biglycan in cancer indicate its pro-tumorigenic function." (PMID 34917515, 2021). "Elevated levels of BGN start to be noticed at stage IB, classified by the presence of cancer cells in the proximal lymph nodes (in the outer muscular layers of the stomach), which may indicate an early event in the invasion and metastatic process." (PMID 33809543, 2021). "In addition, we found the levels of plasma biglycan to be elevated in patients with cancer compared to those in healthy controls." (PMID 32375250, 2020). "Proteoglycans such as biglycan and endocan could be monitored in the blood of patients with cancer as potential biomarkers for companion diagnostics before, during, and after antiangiogenic therapy." (PMID 32375250, 2020). "Furthermore, comparison between the expression of biglycan and Claudin-4 in cancer cells showed that the expression of Claudin-4 was significantly decreased in biglycan (+) cases." (PMID 32821344, 2020). "Plasma biglycan levels in patients with cancer were higher than those in healthy volunteers." (PMID 27295191, 2016). "Cancer cell-derived secretomes induced versican and biglycan expression in fibroblasts." (PMID 25593993, 2014). "Serum biglycan levels were higher in cancer patients than in healthy volunteers." (PMID 22374465, 2012). "Western blotting analysis of biglycan was performed on sera from cancer patients." (PMID 22374465, 2012). "ECM-related genes that promoted the strongest proliferation, including POSTN, BGN type I collagen and type IV collagen, have already been identified as cancer markers, and might be molecular targets for gene therapy." (PMID 17411443, 2007). "However, through literature data, we found that BGN may promote the disease progression of most cancers." (PMID 39650066, 2024). "Furthermore, in the in vivo context, tumors formed by biglycan-negative cells lead to a decrease of the ECM cohesive phenotype that can be associated with a decrease cancer cell survival." (PMID 33809543, 2021). "In this study, we investigated the role of the small, leucine-rich, proteoglycan biglycan that is both an extracellular matrix (ECM) component, but can also act in cell signaling using multiple signaling pathways, and is implicated in the tumorigenesis of different types of cancer." (PMID 35008869, 2021). "However, recombinant biglycan reduced cancer cell migration to a similar extent than nidogen-1." (PMID 30947697, 2019). "Furthermore, serum biglycan levels were higher in cancer patients than in healthy volunteers." (PMID 22374465, 2012). "Significant differences in protein levels were also observed between benign and malignant tumors, for example, the up‐regulation of Translocation protein SEC63 homolog, Annexin A6 and Biglycan in CXPA compared to PA." (PMID 39155517, 2025). "Upregulated hub genes BGN and INHBA exhibited reduced methylation levels, possibly contributing to their overexpression in cancer." (PMID 40898538, 2025). "The RCC score includes a panel of 12 genes, with 7 cancer-related genes (stromal genes: INHBA, BGN, and cell cycle genes: MKI67, MYC, MYBL2, GADD45B) and 5 reference genes, and is used to predict CRC recurrence." (PMID 40664638, 2025). "Our ECM panel for PCC-NOS includes SLRPs like LUM, BGN, PRELP, and ASPN, which exhibit dual functions in cancer." (PMID 39305996, 2024). "The TIMER database was used to analyze the correlation between mRNA expression of APOE, BGN, BST2, and C1QB and infiltrating immune cells in cancer tissues." (PMID 39650066, 2024).
cancer (continued). "Two proteins included in the carcinoma EV signature were the ECM proteins biglycan (BGN) and fibronectin (FN1), which were among the most over-represented ECM-related proteins in EV isolates from all carcinoma cell lines." (PMID 39462388, 2024). "BGN, which is an extracellular protein (ECM) 15, is highly expressed in many human cancers, and predicts poor prognosis." (PMID 36632455, 2023). "Further research exploring the modulation of the transcription, translation, transportation, excretion and extracellular behaviour of BGN will further elucidate its role in the TME and its contribution to cancer development and immunotherapy resistance." (PMID 36772945, 2023). "Recently, a member of the small leucine-rich repeat proteoglycan (SLRP) family, named biglycan (BGN), has been shown as a regulator of MHC class I expression in HER‐2/neu- and K-RAS- transformed cancer cells." (PMID 37730606, 2023). "For example, Oncotype DX tests the expression of 5 reference genes and 12 cancer-related genes, including BGN (biglycan), COL1A1, FLNC, and SFRP4 (secreted frizzled related protein 4)." (PMID 38255186, 2023). "BGN expression in DAB units [median (range)] was 6.2 (0.8 to 12.4) and 27.31 (5.3 to 81.7) in cancer and normal breast tissue, respectively, using D-HScore (p = 0.0017, Mann-Whitney test)." (PMID 36972253, 2023). "In this study, we identified a new molecular target, BGN which was upregulated in both BCSCs (CD29hiCD61+, ALDH+) as compared to bulk cancer cells." (PMID 35053617, 2022). "DCN, BGN, LUM and fibromodulin (FMOD) are the most reported members of SLRPs involved in cancer progression." (PMID 34888227, 2021). "Biglycan (BGN), a member of small leucine rich PGs (SLRPGs), is overexpressed and secreted by various cancers, which is related to the regulation of immunological responses." (PMID 34733848, 2021). "Among the universal DEGs, 4 upregulated genes (BGN, E2F3, PLAU, and SPP1) and 1 downregulated gene (UBL3) were found to be cancer genes already documented in the COSMIC or F-Census databases." (PMID 33542925, 2021). "The expressions of BGN, COMP, COL5A2, and SPARC were further verified using scRNA-seq data between cancer and normal samples." (PMID 34899080, 2021). "It is suggested that biglycan-dependent FAK signaling activation due to biglycan overexpression leads to increased matrix stiffness and enhanced migration of cancer cells." (PMID 32847060, 2020). "The candidate genes including BGN, MMP1, LGALS1, SERPINB5, and TM4SF4 probably correlated with cancer development and the EMT program mediated by the integrated pathway of TGFβ/Snail with TNFα/NFκB." (PMID 28687755, 2017). "To analyse in vivo biglycan expression in TECs, we performed immunofluorescent double staining with anti-CD31 and anti-biglycan antibodies in the frozen sections of 11 human malignant tumours; 6 from kidneys, 3 from lungs, 1 from colon and 1 from liver." (PMID 22374465, 2012). "BGN has been reported to bind both TLR2 and TLR4 in various cell types, including cancer cells." (PMID 41465449, 2025). "Furthermore, BGN negatively correlates with CD8+ T cell infiltration in the TME, thereby promoting cancer dormancy." (PMID 40977686, 2025). "Taken together, although CAF-derived autocrine signaling and BGN’s ability to modulate macrophages have been reported in other cancer types, these mechanisms have not yet been described in ESCC." (PMID 41465449, 2025). "Nevertheless, the higher biglycan abundance in the carcinoma EVs was clearly not due to these differences as MTH53A EVs expressed similar CD9 levels as the complex carcinoma cell lines, but biglycan was hardly detectable." (PMID 39462388, 2024). "Alternatively, BGN, a proteoglycan in the ECM, may serve as a physical barrier to isolate and protect cancer cells from cytotoxic cells." (PMID 36772945, 2023).
cancer (continued). "Although biglycan, asporin and decorin (key constituents of the bone ECM) belong to the class I SLRP, they possess both pro- and anti-tumorigenic potential and have different roles in the pathogenesis of different cancers." (PMID 36765749, 2023). "YKL-40 gene expression was primarily increased in the fibroblast (gene annotation: COL1A, BGN, DCN), myeloid (gene annotation: CD68, LYZ, AIF1), cancer (gene annotation: EPCAM, KRT7, KRT18), and B-cell (gene annotation: CD79A, CD79B) populations in cancer tissue compared to healthy tissue." (PMID 35631632, 2022). "The differences between the in vitro and in vivo proliferation analysis lead us to suggest that the role of biglycan, as an ECM proteoglycan, in cancer survival/proliferation, may be context-dependent." (PMID 33809543, 2021). "Biglycan (BGN) is an important component of ECM proteins belonging to the small leucine-rich proteoglycans family, which has been reported to play an important role in the oncogenesis and progression of different cancers." (PMID 34899080, 2021). "Among all samples tested, including those of patients with nonmetastatic cancer, the highest biglycan levels were found in patients with metastases (red columns)." (PMID 27295191, 2016). "Furthermore, another secretory protein, biglycan (BGN) was found to be upregulated in CAFs compared with normal cancer-adjacent fibroblasts." (PMID 37496657, 2023). "Moreover, secreted factors (for example, thrombospondin 1 (THBS1) and biglycan (BGN)), and growth factors and cytokines (for example, TGFβ, CXCL12/SDF1, CTGF and FGF2), many of which actively control endothelial and cancer cell behaviour, were differentially regulated between iNFs and iCAFs." (PMID 28198360, 2017). "Expression of the BGN gene was found to be higher in carcinoma tissues than in normal tissues." (PMID 24681892, 2014). "Up to date no therapeutic modulators of BGN expression in cancer have been described." (PMID 24223213, 2013). "BGN is involved in various aspects of cancer biology, including cancer cell proliferation, invasion, epithelial–mesenchymal transition, angiogenesis, chemotherapy resistance, and patient prognosis, but the role of BGN during the early stages of cancer has not yet been elucidated." (PMID 32050430, 2020). "COL6A3, COL8A1, CDH11, and CXCL12 were not expressed in either PDAC tissues or normal tissues, and BGN and THBS2 were overexpressed in both cancer and normal tissues." (PMID 33282565, 2020). "While most MDA-MB-231 cancer cells in the brain were biglycan-negative at 4 weeks post-cancer cell injection as analyzed by immunofluorescence, we detected rare biglycan-positive GFP+ cells, confirming the existence of biglycan-expressing cancer cells in vivo at the protein level." (PMID 37456245, 2023).
renal diseases (7 papers, 2011 to 2025). "The uncontrolled regulation of ECM components, such as collagens, proteoglycans, and glycoproteins (e.g. agrin, decorin, versican, biglycan, and laminins), has been described in numerous kidney diseases." (PMID 40524147, 2025). "Biglycan (Bgn) was reported to be increased in several types of renal diseases." (PMID 34762601, 2021). "Furthermore, as a DAMP, biglycan potentiates renal inflammation and fibrotic renal disorders." (PMID 33966638, 2021).
cardiovascular diseases (3 papers, 2021 to 2023). "SLRPs, including LUM, BGN, and DCN, are all crosslinking regulators and are shown to play a role in ECM remodeling and fibrosis in different mouse models of muscular and cardiovascular diseases." (PMID 38130476, 2023).
infection (3 papers, 2012 to 2020). The state of being infected such as from the introduction of a foreign agent such as serum, vaccine, antigenic substance or organism. "Notably, transcripts encoding several structural elements of ECM, such as fibronectin, collagen chains, laminin, and proteoglycans (BGN, DCN), were downregulated, suggesting impaired tissue repair and wound healing cascades at the infection site." (PMID 32244468, 2020). "Because the activation of this network of DAMPs leads to M1 innate immune responses, the down regulation of BGN, DCN, and VCAN during infection could effectively hinder the stimulation of the M1 (pro-inflammatory) mediators used in the current study." (PMID 28727780, 2017). "TLRs/MyD88 was required for inflammasome assembly after infection [vaccinia virus (TLR2/6), Candida albicans (TLR2), Vibrio (MyD88)] and stimulation with DAMPs [biglycan (TLR2/4)], environmental particles [alkane particles (TLR2)] or fungal components [zymosan and mannan (TLR2)]." (PMID 22295065, 2012).
connective tissue disorder (2 papers, 2020 to 2021). A disease involving the connective tissue. "Whereas no previous associations have been reported between VCAN rs11726, BGN rs743641 or rs743642, and shoulder morbidity to date, other polymorphisms in BGN have been implicated in connective tissue disorders such as ACL ruptures." (PMID 34162438, 2021). "Moreover, from the table of top connective tissue disorders, the network of the term “Abnormality of cartilage tissue” for Epi C vs. Ctr group showed upregulation of collagens, biglycan (BGN), CCN2, and SRY-Box Transcription Factor 9 (SOX9)." (PMID 32575510, 2020). "The BGN rs743641 and rs743642 polymorphisms are both located in the 3' UTR gene regulatory region, but have no reported gene expression correlations nor previous associations with connective tissue disorders of the shoulder." (PMID 34162438, 2021).
myopathies (2 papers, 2010 to 2023). "However, no changes were observed in the BGN gene expression level in our study of WB myopathy." (PMID 38130476, 2023).
skeletal dysplasia (2 papers, 2023 to 2024). Any Mendelian diseases that affects growth and development of the skeleton. "A distinct clinical feature, specifically mild skeletal dysplasia, was observed in males carrying a partial deletion of BGN and the 5’-UTR of the neighboring ATP2B3, compared to males with other loss-of-function BGN variants." (PMID 38531898, 2024). "Although loss-of-function of biglycan is determined to be the main pathomechanism underlying MRLS, additional mechanisms are hypothesized to explain the mild skeletal dysplasia on top of typical MRLS features in males carrying these specific deletions." (PMID 38531898, 2024). "IPSC-derived chondrocyte disease models have been shown to exhibit several key aspects of known disease mechanisms of skeletal dysplasias and are therefore considered highly suitable human disease models to study SEMD, biglycan type." (PMID 36640472, 2023).
psychiatric disorder (1 paper, 2023). A disorder characterized by behavioral and/or psychological abnormalities, often accompanied by physical symptoms. "The finding of BGN also indicates the potential relationship of Collagen type genes (the presence of these genes in our work has been described in the earlier paragraph) in the interaction of PD with psychiatric disorders." (PMID 37654790, 2023).
BGN also shares sentences with these, for which no sentence is quoted: pancreatic adenocarcinoma (6 papers); esophageal cancer (3); esophageal squamous cell carcinoma (3); glioblastoma (3); adenoma (2); Glucose intolerance (2); acute kidney injury (1); acute myocardial infarction (1); adenocarcinoma (1); Alzheimer disease (1); atopic asthma (1); Barrett esophagus (1); cardiac hypertrophy (1); cerebral infarction (1); clear cell renal cell carcinoma (1); congenital disorder of glycosylation (1); coronary atherosclerosis (1); cyst (1); diffuse large B-cell lymphoma (1); endothelial dysfunction (1); erosive vitreoretinopathy (1); fibrosis (1); gingivitis (1); glaucoma (1); glomerulonephritis (1); head and neck squamous cell carcinoma (1); hepatitis B (1); Impaired glucose tolerance (1); inflammation (1); ischemia reperfusion injury (1).
A further 17 diseases each share a sentence with BGN in 1 paper.